CTCF (CCCTC-binding factor)
Diseases named in the same sentence as CTCF in open-access papers (continued):
Sharing a sentence is not in itself a finding about the gene and the disease.
cancer (continued). "Interestingly, mutations within the CTCF NCR that alter its electronic charges are associated with several types of cancers." (PMID 39720519, 2024). "And CTCF/cohesin binding sites are a major mutational hotspot in the cancer genome." (PMID 38463168, 2024). "Recently, extensive research has focused on the association between CTCF and cancer." (PMID 38658701, 2024). "Using an inducible mouse ESC complementation system, we combined imaging,structural, molecular and bioinformatic analyses to examine the impact of nine, highfrequency cancer associated CTCF mutations in eight amino acid residues of ZFs that makecontact with the core consensus binding motif." (PMID 39070636, 2024). "CTCF has been associated with mediating replicative senescence through its interactions with DNA polymerase and the induction of an inflammatory signature in senescence and cancer." (PMID 37706427, 2023). "Such disruptions of hydrogen binding, electrostatic interactions, and zinc finger stabilization by single-residue mutations of CTCF provide atomic-level insights into the molecular mechanisms that can explain the relationship between CTCF mutations and the development of human cancers." (PMID 37047368, 2023). "Thus, the disruption of CTCF–DNA binding by mutations or post-translational modifications often results in the development of various cancers, including endometrial, Wilm’s, and breast cancers." (PMID 37047368, 2023). "The CTCF occupancy reduction may happen due to mutations in the binding sites, which undergo a high mutational load in different types of cancer." (PMID 36468037, 2022). "The overexpression of cancer-associated CTCF mutants partially rescued the insulator activities." (PMID 36117989, 2022). "Interestingly, CTCF sites surrounding SNAI1 are enriched for noncoding mutations in cancer, and SNAI1 was among the top hits within the EMT pathway based on our RNA-seq data." (PMID 36037342, 2022). "Of note, multiple mutations map to the DNA-binding zinc finger domain of CTCF across cancers." (PMID 36589746, 2022). "CCCTC-binding factor (CTCF) is a highly conserved zinc finger protein that regulates high-order chromatin tissue and participates in various gene regulatory processes, which is often altered by hemizygous deletions or mutations in human cancers." (PMID 35693981, 2022). "Interestingly, the analysis of the COSMIC database using the entire CTCF open reading frame as a query indicated that the CTCF DBD is a cancer mutation hotspot." (PMID 36117989, 2022). "Cancer-associated arginine mutations in the CTCF DBD interfered with its DNA-binding and insulation functions, so we considered whether these findings might point toward a potentially widespread mechanism in cancer." (PMID 36117989, 2022). "It will be important to determine whether and how the gain of CTCF might favour cancer development and whether the gain of CTCF copies constitutes a cause or a consequence of oncogenic pathway activation." (PMID 35993175, 2022). "Interestingly some cancer‐related point mutations in CTCF affect the individual ZFs of CTCF thereby altering its genomic binding profile." (PMID 35993175, 2022). "CCCTC-binding factor (CTCF) is a well-known regulator facilitating chromatin into topologically associated domains by enhancing cohesin-mediated loop formation, which is strongly associated with cancer initiation." (PMID 35814454, 2022). "Also, the cosine similarity between the profile context of the CTCF regulatory mutations in these cancer types and SBS17b was between 0.6 and 0.72." (PMID 34282050, 2021). "In addition, CTCF has been proposed as a tumor suppressor gene, since mutations in its coding sequence have also been detected in different types of cancer." (PMID 34295901, 2021).
cancer (continued). "Moreover, given the extensive characterization of CTCF as a tumor suppressor gene, its frequent mutation in cancer and loss- or gain-of-function phenotypes, causal links between CTCF-mediated aberrant AS and cancer are likely to emerge." (PMID 34181707, 2021). "This methylation/expression paradox in mutation-free cancers was interpreted as a consequence of hypermethylation that might interfere with CTCF (CCCTC-binding factor) transcription repressor binding." (PMID 34639089, 2021). "Additionally, the BORIS/CTCF mRNA expression ratio is also linked with DNA hypomethylation in cancers." (PMID 34788504, 2021). "Loss of CTCF-mediated insulation has been identified as a potential reason for domain disruption and spreading and has been connected with multiple malignancies, such as cancer, intellectual disability and developmental disorders." (PMID 31945090, 2020). "In contrast to most genes, TERT promoter hypomethylation could be associated to its transcriptional repression in cancer, suggesting that tert promoter sequences may be a binding site for the CTCF/cohesin complex." (PMID 33266037, 2020). "Despite the finding that CTCFL is aberrantly expressed in numerous cancers, little is known about its impact on chromatin organization and gene regulation and the mechanism underlying its effector functions and interplay with CTCF." (PMID 32393311, 2020). "CTCF, a well-known transcription factor that is essential in organizing chromatin into highly self-interacting, topologically associated domains, has recently become of great interest to researchers in the cancer field." (PMID 33665169, 2020). "We then questioned whether CTCF loss in vivo has an impact on hypermethylation patterns in human cancers." (PMID 32503656, 2020). "Therefore, mutations in the CTCF gene can have far-reaching effects on initiation and development of cancer." (PMID 31852961, 2019). "However recent cancer genome studies have revealed the extensive somatic mutations occurring in CTCF." (PMID 30513694, 2018). "Some cancers with lower MSI incidence may have other underlying defects that promote CTCF mutations, such as APOBEC deaminases abnormalities." (PMID 30275357, 2018). "CTCF is also implicated as a haploinsufficient tumor suppressor gene in human cancers." (PMID 30086769, 2018). "Our results suggest that these two PCa risk-associated CTCF sites may function by encaging cancer-relevant genes in repressive loops." (PMID 30296942, 2018). "We therefore speculate that in lesions that contain this variant of HPV16, CTCF may bind with higher affinity and have a more significant effect on the attenuation of E6/E7 expression, thereby reducing the risk of cancer development." (PMID 30359362, 2018). "Indeed, we observed an even more marked enrichment for mutations in ZNF263 sites in cancers than CTCF (p value = 7.58 × 10−14)." (PMID 29540241, 2018). "The extent to which similar CTCF repositioning is involved in other cancer contexts, including metastasis, remains unclear, but there is evidence that CTCF/cohesin binding sites can accumulate mutations in several cancers." (PMID 27756687, 2017). "However, there is also a confusing association with CTCF in relationship between viral replication and cancer." (PMID 27632082, 2016). "Interestingly, we uncovered a significant increase in deleterious mutations of CTCF, which is a master chromatin regulator associated with genomic instability and cancer progression." (PMID 26747525, 2016).
cancer (continued). "However, an excess of mutations inside loop anchor motifs was observed in all cancer types with a sufficiently high number of CTCF mutations, i.e. whenever the power to detect this difference in mutation rates at alpha = 0.05 was 80% or greater." (PMID 27490693, 2016). "Interestingly, CTCF/cohesin sites are frequently mutated in cancer and somatic substitutions accumulate immediately adjacent to the CTCF core motif (10–14 bp upstream of center of the G rich CTCF motif)." (PMID 27582050, 2016). "It has been proposed that architectural proteins such as CTCF may be associated with widespread changes to the cancer methylome in addition to alterations in the physical packaging of chromatin and perhaps phasing." (PMID 24916973, 2014). "On one hand, it is believed that BORIS could participate in the molecular mechanisms driving cancer behaving as oncogene; on the other hand, an ancillary role when CTCF is mutated and the encoded protein is dysfunctional has been proposed in a recent report." (PMID 25114808, 2014). "Testis-specific transcription factor BORIS (Brother of the Regulator of Imprinted Sites), a paralog and proposed functional antagonist of the widely expressed CTCF, is abnormally expressed in multiple tumor types and has been implicated in the epigenetic activation of cancer-testis antigens (CTAs)." (PMID 22792300, 2012). "Furthermore, point mutation and loss of heterozygosity of CTCF is associated with human cancer, identifying CTCF as an important candidate tumour-suppressor gene." (PMID 18769711, 2008). "Therefore, our observations hint at the potential therapeutic effectiveness of HATi to block the epigenetic shifts necessary for tumor progression, which could be more effective in CTCF-deficient cancers." (PMID 36037342, 2022). "Together, these results point toward a potentially important role for the loss of heterozygosity of CTCF in cancer progression, as it promotes disorganized 3D growth and invasiveness, two strongly linked oncogenic abilities critical for tumors to progress from benign to advanced stages of cancer." (PMID 36037342, 2022). "Overexpression of the 14q32 cluster miRNAs has been associated with the CCCTC-binding factor (CTCF)-mediated regulation of the maternally expressed gene 3 differentially methylated region (MEG3-DMR) or global genomic hypomethylation of 14q32 locus as reported in various cancers, including CLL." (PMID 34750354, 2021). "Furthermore, CTCF has been associated with epithelial-to-mesenchymal transition—a developmental process via which cells gain migratory and invasive properties that can be hijacked during cancer metastasis." (PMID 32374727, 2020). "Therefore, CTCF CN loss tumors have increased hypermethylation CTCF intact cancers." (PMID 32503656, 2020). "CTCF has been shown to co-bind DNA with other factors to establish DNA loops and control gene expression; thus, we looked for TFs potentially involved in cancer-specific CTCF gain events that associate with dynamic chromatin interaction and increased gene expression." (PMID 32933554, 2020). "Moreover, we identified four novel candidate cancer-associated genes (CTCF, ARHGAP35, NF1, and KDR) which may be crucial in the carcinogenesis of EEC." (PMID 30886832, 2019). "The distribution of mutations within functional CTCF TFBSs in our dataset was significantly different from that of 1KG polymorphisms (Fisher’s exact test, p < 10−5), with the central nucleotide known to be constrained at the population level but highly mutated in cancer." (PMID 27490693, 2016).
cancer (continued). "Disrupting the spectrum of target specificities of CTCF by mutations, its aberrant modifications (e.g. PARylation) or abnormal selective methylation of targets (e.g. loss of imprinting) could be associated with cancer." (PMID 25352953, 2014). "Thus, in cancer a deregulation of CTCF-PARP-1 poly(ADP-ribosyl)ation levels may cause the activation of Dnmt1 and the local hypermethylation of the Rb promoter." (PMID 21663659, 2011). "Instead, the role of CTCF in promoting the DDR has primarily been explored in cancer studies, wherein CTCF is considered a tumor suppressor gene." (PMID 41338928, 2026). "In most cancers, cancer cells utilize methylation of the hTERT promoter to evade CTCF-mediated repression near the proximal exon region of hTERT." (PMID 39871386, 2025). "Meanwhile, lncRNAs mainly focused on binding proteins such as STAT3 and CTCF, as well as cancer features such as invasion, metastasis, and epithelial–mesenchymal transition." (PMID 40444278, 2025). "To compare mitotic chromosome binding of CTCF in previously studied cancer cell lines, we synchronized U2OS and HeLa cells in mitosis and subjected them to IF staining for CTCF without fixation." (PMID 40161611, 2025). "The uniqueproperties of WT and mutant CTCF also effect TF binding and cancer, brain, immune andmetabolic gene expression pathways." (PMID 39070636, 2024). "We mainly focus on the role of CTCFL in testicular and cancer development, highlighting its interaction with CTCF at CTCF binding sites to regulate target genes." (PMID 39430552, 2024). "CTCF expression was upregulated in various types of cancer tissues including LUSC tissues in comparison with normal tissues, as analyzed through the TIMER database." (PMID 39506204, 2024). "To elucidate the impact of the cancer-associated mutations on CTCF’sbinding dynamics, we performed fluorescence recovery after photobleaching (FRAP) on the 9mutants and wild-type CTCF 31,32." (PMID 39070636, 2024). "Among these genes, we can find some encoding cancer-relevant transcription factors such as E2F1 CTCF, and ERG and DNA methyltransferase enzymes (DNMT1)." (PMID 38773638, 2024). "In contrast, clustered CTCF binding sites (2xCTSes) are co-bound by CTCF and BORIS and are associated with active transcription in germ and cancer cells." (PMID 38297316, 2024). "Using various cell models with endogenous and ectopic BORIS expression, we show that hundreds of testis-specific transcripts are aberrantly expressed in cancer cells from CTCF and BORIS co-bound transcriptional start sites." (PMID 38297316, 2024). "The disruption of CTCF sites triggers the disruption of TAD boundaries, and mutations of CTCF/cohesion-binding motifs are frequently observed in many cancers." (PMID 39796070, 2024). "Using different cell systems with modified levels of BORIS protein, we demonstrated that BORIS co-binding with CTCF is essential for the activation of such alternative testis-specific promoters in cancers." (PMID 38297316, 2024). "In summary, CTCF is a multifaceted protein with a wide range of functions, and its dysregulation can contribute to various diseases, particularly cancer and developmental disorders." (PMID 38658701, 2024). "Intriguingly, in human cancer cells, the cohesin component Rad21 and the chromatin organizing factor CTCF bind to TERRA promoters and control TERRA transcription." (PMID 37636218, 2023). "This transcription factor, aberrantly expressed in cancer, competes for binding sites with its somatic analog CTCF, alters the epigenetic landscape, and even induces the transformation of mouse fibroblasts during ectopic expression." (PMID 36983050, 2023). "CTCF emerged by duplication of the gene during the evolution of amniotes that in human cancer is being proposed to act like an oncogene by dysregulation of cancer epigenome." (PMID 37235839, 2023). "Because CTCF can suppress tumor formation by limiting the expression of oncogenes, altered TADs are related to cancer development." (PMID 37047368, 2023).
cancer (continued). "ChIP-seq reveals that the conserved CTCF binding site within the HPV genome binds CTCF in 4 HPV﻿+ cancer cell lines." (PMID 37365652, 2023). "Our results indicated that these new approaches effectively re-discover CTCF’s cofactors, as well as cancer-specific and oligodendrocytes-specific master regulators implicated in disease and cell type development." (PMID 37600846, 2023). "CTCF somatic mutations can occur in CRC40, and indeed a mouse model of chronic CTCF hemizygosity led to higher cancer incidence and dysregulation of oncogenic pathways." (PMID 36289335, 2022). "The FOXM1 promoter contains CTCF binding site, and CTCF transcriptionally activates FOXM1 in cancer." (PMID 35378133, 2022). "Here, we examine the contribution of major chromatin organizers, namely CTCF, cohesins, and condensins, to cancer progression." (PMID 36589746, 2022). "Studies in the highly invasive MDA-MB-231 and the less invasive MCF-7 cells show that CTCF-dependent Nm23-H1 levels inversely correlate with cancer aggressiveness." (PMID 36589746, 2022). "It supposes that at least a portion of the cancer-specific changes in CTCF occupancy is related to a change in DNA methylation of the binding sites." (PMID 36468037, 2022). "We summarize recent findings linking CTCF to cell differentiation and disease with a special focus on cancer and neurological disorders." (PMID 35993175, 2022). "We have previously reported that BORIS is located in both the cytoplasm and nucleus in cancer cells; in contrast, CTCF is located only in the nucleus." (PMID 35918747, 2022). "CTCF has been revealed as a critical transcriptional factor to mediate long noncoding RNAs (lncRNAs) to affect cancer progression." (PMID 35693981, 2022). "The depletion of CTCF in cancer cells was performed by electroporation-mediated delivery of an esiRNA pool targeting the human CTCF transcript." (PMID 35409255, 2022). "The genome-wide comparison between CTCF occupancy and DNA methylation indicates that in cancer cells, CTCF losses are accompanied by the DNA methylation increase, whereas a lot of gained CTCF are in the demethylated region." (PMID 36468037, 2022). "This splicing is controlled through DNAm states of alternative promoters, PCDH cluster expression involving CTCF interaction, which can be affected by methylation alterations, leading to long-range epigenetic silencing in cancers." (PMID 36551712, 2022). "This study further reveals that drug-induced hypomethylation using 5-aza-2 deoxycytidine (5dAza) rescued chromatin organization, reaffirming the importance of CTCF and its binding sites in cancers." (PMID 36589746, 2022). "CTCF functions as a double-edged sword, acting both as an oncogene as well as a tumor suppressor in a cancer subtype-specific manner." (PMID 36589746, 2022). "SVs often overlap with binding sites for the transcriptional regulator, CTCF, near proto‐oncogenes of certain cancer types, potentially resulting in disruption of CTCF‐CTCF chromatin folding loops." (PMID 35355264, 2022). "For example, transcription start sites of highly expressed genes and constitutively-bound binding sites of CTCF are subject to elevated local mutagenesis in multiple cancer types." (PMID 35947558, 2022). "Addition to CTCF and cohesin, Brother of The Regulator of Imprinted Sites (BORIS, also known as CTCFL) is an emerging architectural protein, which is a paralog of CTCF and typically expressed in testis and ESCs but aberrantly overexpressed in several cancers." (PMID 33453053, 2021). "We have also observed quite variable CTCF protein abundance in primary HMECs, fibroblasts, cancer cell lines, and during differentiation of human pluripotent stem cells (hPSC), using primarily an N-terminal CTCF polyclonal antibody (Active Motif)." (PMID 33411704, 2021).